EPS15 (epidermal growth factor receptor pathway substrate 15)
Description:
Involved in cell growth regulation. May be involved in the regulation of mitogenic signals and control of cell proliferation. Involved in the internalization of ligand-inducible receptors of the receptor tyrosine kinase (RTK) type, in particular EGFR. Plays a role in the assembly of clathrin-coated pits (CCPs). Acts as a clathrin adapter required for post-Golgi trafficking. Seems to be involved in CCPs maturation including invagination or budding. Involved in endocytosis of integrin beta-1 (ITGB1) and transferrin receptor (TFR); internalization of ITGB1 as DAB2-dependent cargo but not TFR seems to require association with DAB2.
Synonyms: AF1P; AF-1P; MLLT5
Tractability: Antibody: UniProt places it where antibodies can reach, with high confidence; its Gene Ontology location is reachable by antibodies, with high confidence. PROTAC: UniProt records ubiquitination sites on it; ubiquitination databases record sites on it; its protein half-life has been measured; a small molecule that binds it is known.
Gene: Protein-coding gene on chromosome 1 (51,354,263 to 51,519,387, reverse strand). Ensembl gene ENSG00000085832.
Subcellular location: Cytoplasm; Cell membrane; Membrane, clathrin-coated pit; Early endosome membrane (Isoform 2)
Subcellular location (Human Protein Atlas): Cytosol; Vesicles
Pathways (Reactome):
Signal Transduction: EGFR downregulation; Negative regulation of MET activity
Vesicle-mediated transport: Cargo recognition for clathrin-mediated endocytosis; Clathrin-mediated endocytosis
Cell-Cell communication: Degradation of CDH1
Disease: InlB-mediated entry of Listeria monocytogenes into host cell
Gene Ontology:
Molecular function: cadherin binding; polyubiquitin modification-dependent protein binding; protein binding; protein-macromolecule adaptor activity; calcium ion binding; identical protein binding; ubiquitin binding
Biological process: clathrin coat assembly; Golgi to endosome transport; receptor-mediated endocytosis of virus by host cell; symbiont entry into host cell; endocytic recycling; vesicle organization; endocytosis; positive regulation of receptor recycling; postsynaptic neurotransmitter receptor internalization; regulation of cell population proliferation; ubiquitin-dependent endocytosis
Cellular component: aggresome; cytosol; membrane; plasma membrane; clathrin coat of coated pit; clathrin-coated pit; AP-2 adaptor complex; apical plasma membrane; basal plasma membrane; ciliary membrane; clathrin-coated vesicle; cytoplasm; early endosome; early endosome membrane; glutamatergic synapse; postsynaptic endocytic zone; synapse
Genetic constraint (gnomAD): Loss-of-function variants: 38 observed, 58.68 expected, observed/expected ratio (o/e) 0.65, 90% interval 0.5 to 0.85. The upper end of that interval is the gene's LOEUF score, 0.85, which puts it in group 3 of 6, group 1 being the genes least tolerant of losing a copy. Missense variants: 629 observed, 655 expected, observed/expected ratio (o/e) 0.96, 90% interval 0.9 to 1.03. Synonymous variants: 209 observed, 231.19 expected, observed/expected ratio (o/e) 0.9, 90% interval 0.81 to 1.01.
Cancer hallmarks: proliferative signalling (promotes)
Homologues: Orthologues: chimpanzee EPS15 (99% identical), macaque EPS15 (98% identical), rabbit EPS15 (94% identical), dog EPS15 (92% identical), pig EPS15 (91% identical), guinea pig EPS15 (90% identical), rat Eps15 (90% identical), mouse Eps15 (89% identical), tropical clawed frog eps15 (64% identical), zebrafish eps15 (58% identical), Drosophila melanogaster Eps-15 (32% identical), Caenorhabditis elegans ehs-1 (25% identical), and 2 more. Paralogues in human: EPS15L1 (49% identical), ITSN1 (22% identical), ITSN2 (21% identical), REPS1 (16% identical), REPS2 (14% identical), EHD4 (11% identical), EHD1 (11% identical), EHD3 (10% identical), EHD2 (10% identical), SRL (7% identical).
Diseases named in the same sentence as EPS15 in open-access papers:
EPS15 is named in the same sentence as 29 diseases in open-access papers, as found by Europe PMC text mining. Sharing a sentence is not in itself a finding about the gene and the disease. The quoted sentences say what the papers report.
breast carcinoma (3 papers, 2014 to 2025). "In addition to affecting cell migration and cancer-related signal transduction, eps15 is also associated with poor prognosis in various tumor types, including breast cancer, esophageal squamous cell carcinoma, and glioma." (PMID 35211158, 2022). "As a crucial player in terminating growth factor signaling, EPS15 plays an important role in many malignancies, including breast cancer.18) CFHR2 is involved in regulation of the complement cascade and is responsible for the immune response and inflammatory control." (PMID 40678018, 2025).
lung carcinoma (3 papers, 2017 to 2024). "USP14 controls epidermal growth factor receptor (EGFR) fate in lung cancer by deubiquitinating the endocytic adaptor Eps15." (PMID 39164728, 2024). "It is possible that a similar process occurs in lung cancer, also involving the EGFR binding partners EPS15 and PACSIN2." (PMID 34684727, 2021).
viral infection (3 papers, 2019 to 2023). "In addition, we transfected the WT or the DN constructs of EPS15, one of the adaptors involved in CME, into PK15 cells prior to PCV3 infection to determine the effects of overexpression upon viral infection." (PMID 33679671, 2021). "Furthermore, overexpression caveolin DN mutant and siRNA against caveolin also decreased virus titers and VP1 protein synthesis, whereas overexpression EPS15 DN mutant and siRNA against EPS15 did not reduce virus infection." (PMID 30909932, 2019).
acute myelogenous leukemias (2 papers, 2009 to 2024). "Fusion of Eps15 to transcription factors has been found in certain forms of acute myeloid leukemia (AML), where Eps15 is fused to the mixed lineage leukemia gene (MLL)." (PMID 19814798, 2009).
liver cancer (2 papers, 2022). An epithelial or non-epithelial malignant neoplasm that arises from the liver. "In addition, TSC1 overexpression resulted in poor outcomes in liver cancer patients (p < 0.05), but DCAF7 and EPS15 might not be associated with poor outcomes in liver cancer patients (both p > 0.05)." (PMID 35655269, 2022).
anemia (1 paper, 2020). A reduction in the number of red blood cells, the amount of hemoglobin, and/or the volume of packed red blood cells. "Iron deficiency-induced anemia is present in hematopoietic-specific conditional Eps15/Eps15L1-double-KO mice." (PMID 32943616, 2020).
asthma (1 paper, 2023). "Moreover, the differentially co-expressed genes, both up- and down-regulated in EA, were previously linked to asthma in the genome- (e.g., MRPL14, ASB3, RHOBTB2) and epigenome-wide (e.g., CLC, EPS15, GPI, SRCRB4D, STRN4) association studies." (PMID 36835202, 2023). "Among the differentially co-expressed genes, eight were previously linked to asthma in genome- (MRPL14, ASB3, RHOBTB2) and epigenome-wide (CLC, EPS15, GPI, SSCRB4, STRN4) association studies and five were mentioned in the literature in the context of asthma (SLC19A1, MAEA, CLC, ATP1B1, and RECK)." (PMID 36835202, 2023). "Affinity capture studies indicate interactions between the protein products of RPS13, CCT7, and EPS15 and proteins involved in cell–cell and cell-ECM adhesion molecules relevant for asthma, such as VCAM-1, α4β1 integrin, and fibronectin." (PMID 36835202, 2023).
dengue (1 paper, 2009). "A combination of biochemical inhibition, dominant negative transfection of Eps15 and siRNA mediated gene silencing was used to explore the entry mechanism of dengue into HepG2 cells." (PMID 19272179, 2009).
glioblastoma (1 paper, 2024). The most malignant astrocytic tumor (WHO grade IV). "The mRNA expression of EPS15 and KIF5A was significantly downregulated in both the TCGA and REMBRANDT glioblastoma datasets, and EHD2 was upregulated in both datasets." (PMID 38638676, 2024).
influenza (1 paper, 2025). An acute viral infection of the respiratory tract, occurring in isolated cases, in epidemics, or in pandemics; it is caused by serologically different strains of viruses (influenzaviruses) designated A, B, and C, has a 3-day incubation period, and usually lasts for 3 to 10 days. "Similar to our results, influenza was shown to employ clathrin-coated vesicles as a non-exclusive mode of entry into cells, but inhibition of clathrin-mediated endocytosis via expression of the Δ95-295 mutant of Eps15 or chlorpromazine failed to inhibit influenza infection in HeLa cells." (PMID 39981379, 2025).
intracerebral hemorrhage (1 paper, 2022). A cerebrovascular disorder characterized by bleeding into one or both cerebral hemispheres including the basal ganglia and the cerebral cortex. "It has been found that in intracerebral hemorrhage (ICH), microglial activation marker CD68 was co-located with EHD2, a member of the Eps15 homology domain (EH domain) family." (PMID 36712438, 2022).
malaria (1 paper, 2023). Malaria is a serious and sometimes fatal disease caused by a parasite that commonly infects a certain type of mosquito which feeds on humans. "The BioID proxiome of K13 and Eps15 revealed the first proteins involved in the initial steps of endocytosis in malaria parasites, a process that in blood stage parasites leads to the uptake of large quantities of host cell cytosol." (PMID 38039338, 2023).
melanoma (1 paper, 2016). A malignant, usually aggressive tumor composed of atypical, neoplastic melanocytes. "Given that TOLLIP, EPS15, and TAX1BP1 were isolated from a human melanoma cell line using a proteomic approach, it stands to reason that other vesicle-associated adaptor proteins expressed in other cell types could exhibit a similar relationship with RNF26." (PMID 27368102, 2016).
rheumatoid arthritis (1 paper, 2023). A chronic, systemic autoimmune disorder characterized by inflammation in the synovial membranes and articular surfaces. "Another study identified a potential role for the EPS15 gene in white blood cells in predicting response to infliximab in rheumatoid arthritis." (PMID 38203588, 2023).
infection (18 papers, 2008 to 2022). The state of being infected such as from the introduction of a foreign agent such as serum, vaccine, antigenic substance or organism. "Quantification of the transfected/infected cells showed a significant reduction in infection of about 60% (p < 0.001) for the Eps15-DN condition relative to the Eps15-WT for both viruses." (PMID 36008558, 2022). "The other differentially regulated microarray target gene, EPS15, also increased, but only 36 h post-infection." (PMID 23472054, 2013). "In TE671 cells, the Eps15-DN rather enhanced the CD4-dependent HIV-1 vector infection provably due to elevated expression of CXCR4." (PMID 21541353, 2011). "In contrast, infection was unaffected by expression of a mutant of the clathrin endocytic pathway (Eps15) in HBMEC." (PMID 20949071, 2010). "The Eps15-DNM inhibited fusion in all three infection conditions, albeit to a different extent." (PMID 27385443, 2016). "The percentage of infection was similar in cultures transfected with wt or DN Eps15." (PMID 26469784, 2015). "Most KSHV particles were colocalized with both Epsin and Eps15 during infection of HUVEC." (PMID 22615563, 2012). "Here we report that BTV-1 infection of BHK cells is also dependent on a low endosomal pH; however, virus entry and infection were not inhibited by dominant-negative mutants of Eps15, AP180 or the ‘aa’ splice variant of dynamin-2, which were shown to inhibit clathrin-mediated endocytosis." (PMID 20613878, 2010). "Taken together with the effect of clathrin heavy chain, dynamin-1, or Eps15 siRNAs on HMPV infectivity, these data indicate that CME of HMPV during entry leads to productive infection of human bronchial epithelial cells." (PMID 26629703, 2015). "We found that the knock-down of four genes (DNM3, IDH3G, EPS15 and ATP6AP1) significantly inhibits HIV-1 replication, especially at later time-points (from four to seven days post-infection)." (PMID 25496667, 2014). "The endocytosis inhibitors, dynasore and Eps15-DN, suppressed the CD4-independent HIV-1 vector infection, showing that the CD4-independent infection occurs through endosomes." (PMID 21541353, 2011). "Thus, while Eps15, dynamin-1, dynamin-2, dynamin-3, and clathrin heavy chain siRNAs inhibited HMPV entry and diminished infection, cells that did become infected exhibited normal amounts of surface F protein." (PMID 26629703, 2015). "The Eps15-DN suppressed the CD4-independent mNDK infection, but not the CD4-dependent infection under conditions that the levels of Eps15-DN expression in the CD4-negative and –positive cells were similar." (PMID 21541353, 2011). "Expression of DN Eps15 and dynamin II markedly reduced infection with rVSVΔG-VSVG, but not the arenavirus pseudotypes." (PMID 21931550, 2011). "Suppression of endosome acidification or endocytosis by inhibitors or by an Eps15 dominant negative mutant reduced the infectivity of mNDK in which CD4-dependent infections were not significantly impaired." (PMID 21541353, 2011). "Here we have investigated the involvement of the clathrin pathway in BTV-1 entry and infection of BHK cells using deletion mutants of AP180 (AP180C) and Eps15 (Eps15-Ed95/295; from here known as DN-Esp15) which act as DN inhibitors of CME and block uptake of transferrin." (PMID 20613878, 2010). "Consistent with a role for early and late endosomes and in contrast to the lack of effect of DN Eps15 and Cav-1 expression, GFP-tagged DN Rab5 or DN-Rab7 resulted in significant reduction (P<0.001 for each) in infection by gfpZEBOV." (PMID 20862315, 2010). "Similarly, siRNA against EPS15 and EPS15 DN mutant transfection did not significantly alter PSV infection, indicating that PSV entry IPEC-J2 cells may be independent of CME." (PMID 30909932, 2019).
tumor (9 papers, 2017 to 2025). "USP9X has been shown to regulate EGFR endocytosis in tumor cell lines by deubiquitinating its endocytic adaptor Eps15 and ubiquitin ligase Itch." (PMID 36653359, 2023). "Comparing the expression of the CDDP-DTP-associated genes between tumor and normal adjacent tissue, and its clinical relevance, we found that six (GADD45A, SOCS1, EPS15, GLI3, NR2F2, and RCOR1) of the hub genes have significant differences." (PMID 37916165, 2023). "USP9X has been reported to simultaneously regulate endocytosis of the EGFR by deubiquitinating its endocytic adaptor Eps15 and ubiquitin ligase Itch in tumor cell lines." (PMID 35389885, 2022). "In contrast, the expressions of SOCS1, EPS15, GLI3, NR2F2, and RCOR1 were significantly decreased in tumor compared to normal tissue (p < 0.05)." (PMID 37916165, 2023). "Seven of the 64 tumour suppressors (ACVR2A, CSMD3, EPS15, MAP2K4, NF1, PBRM1 and RB1) had intronic mis-splicing mutations in multiple tissues." (PMID 33420369, 2021).
cancer (6 papers, 2013 to 2025). A tumor composed of atypical neoplastic, often pleomorphic cells that invade other tissues. "Mutations in EPS15 have been shown to be associated with cancers with abnormalities in the EGFR pathway." (PMID 40678018, 2025). "Some of these proteins, including Rpl21, Atic, Eif3s2, Echs1, Eps15 and Ywhab, have previously been reported to be involved in cancer genesis and progression." (PMID 23895178, 2013). "Among them, pORF-HGFK1 exhibited significantly more potent effects on Eps15, CK18, and CK8 compared to pEndo, suggesting that these three proteins may have contributed to the anti-cancer stem-cell activity of HGFK1." (PMID 38794215, 2024). "EHD1, a protein of the C-terminal Eps15 homology domain-containing (EHD) family, plays a role in regulating endocytic recycling, but the mechanistic details involved in EGFR-TKI resistance and cancer stemness remain largely unclear." (PMID 29549343, 2018).
EPS15 also shares sentences with these, for which no sentence is quoted: leukemia (3 papers); adenocarcinoma (1); airway hyperresponsiveness (1); cervical cancer (1); colon cancer (1); eosinophilia (1); esophageal squamous cell carcinoma (1); glioma (1); Globozoospermia (1); mastocytosis (1); phyllodes tumor (1); schizophrenia (1).